MSTN (myostatin)
Diseases named in the same sentence as MSTN in open-access papers (continued):
Sharing a sentence is not in itself a finding about the gene and the disease.
Obesity (continued). "Muscle aging is associated with diabetes and obesity, and in the present study, we compared the expressions of the FMOD and MSTN genes and those of genes related to muscle aging (Atrogin 1, Glb1), diabetes (RAGE, CD163) and intracellular lipid accumulation (CD36, PPARγ) in vivo and in vitro." (PMID 34440852, 2021). "It is not known whether beige fat activation contributes to the protection from obesity in myostatin null mice." (PMID 33220490, 2021). "Our study showed that serum myostatin levels in patients with obesity may be regulated not only with the absolute skeletal muscle mass but also with their BW ratio." (PMID 33465151, 2021). "In addition, in high-fat-induced obesity, MSTN is overexpressed in leucocytes and spleen, suggesting its role as a mediator of inflammation." (PMID 32286342, 2020). "Interestingly, in subjects with obesity, both muscle myostatin expression and circulating follistatin levels decreased after weight loss due to bariatric surgery, in parallel with the decrease in LBM and the increase in insulin sensitivity." (PMID 32316563, 2020). "Despite the abnormal MSTN regulation in insulin resistance, atherosclerosis, obesity and diabetes, the possible direct role of MSTN in diabetic nephropathy (DN) is unknown." (PMID 32286342, 2020). "This requires confirmation because of the key significance of the myostatin/IL-6 balance in the fat infiltration/apoptosis/failure of injury repair occurring in obesity and diabetes where stem cell damage may be a key." (PMID 31430893, 2019). "MSTN inhibition induce a reduction of fat in obesity and osteoporosis and has also been suggested for other diseases in which cachexia is present such as cancer, acquired immune deficiency syndrome (AIDS), obstructive chronic pulmonary disease, and renal failure." (PMID 30717377, 2019). "Because obesity and insulin resistance increase the expression of myostatin, changes in skeletal muscle mass may be affected by metabolic syndromes, including diabetes mellitus and sarcopenic obesity." (PMID 30754663, 2019). "Among these myokines, myostatin regulate glucose and lipid metabolism, and myostatin-deficient animal are not susceptible to diet-induced obesity." (PMID 31683535, 2019). "Moreover, obesity upregulates myostatin (GDF-8), a member of the transforming growth factor-β (TGF-β1) family, FoxO, inducible nitric oxide synthase and Csp3; all members of the muscle atrophy pathway." (PMID 30286093, 2018). "Therefore, pharmacological blockage of the myostatin/ActRIIB pathway is being actively pursued as a potential strategy for the treatment of muscle wasting diseases, and obesity." (PMID 29541418, 2018). "Adipose tissue-specific MSTN overexpression also increases resistance to diet-induced obesity." (PMID 28344633, 2017). "Currently, it is unclear if the inhibition of myostatin could be used as an approach to treat human obesity and insulin resistance." (PMID 28432282, 2017). "Since then, several groups have investigated whether the myostatin signalling inhibition can be an effective strategy against obesity and insulin resistance." (PMID 26644908, 2015). "Intriguingly, our datasets provide comprehensive evidence against the protective role of myostatin deletion with regard to the development of obesity in the adult as well as perturbing the foetal muscle development programme following exposure to a high-fat diet." (PMID 26644908, 2015). "In addition, transgenic expression of the myostatin propeptide, a molecule that maintains myostatin in an inactive form, is proposed to be protective against high-fat diet-induced obesity." (PMID 26644908, 2015). "Work in murine models and humans has identified that myostatin may have an important role in obesity development." (PMID 25390640, 2014). "Meanwhile, MSTN knock out enhances systemic insulin sensitivity and prevents obesity." (PMID 25859286, 2014).
Obesity (continued). "Together, these results provide further basis for the speculation that myostatin and its receptor may play a role in obesity in horses and ponies." (PMID 25390640, 2014). "The association of muscle myostatin mRNA (but not plasma myostatin) with impaired insulin sensitivity, increased triglyceride, and obesity was observed only in the healthy controls, but not in type 2 DM patients." (PMID 25254550, 2014). "Although myostatin is well known for its role in regulation of muscle growth, it is not clear to what extent myostatin contributes to impaired muscle regeneration observed in rodent models of obesity." (PMID 24381559, 2013). "Hence, several recent studies have also investigated the effects of genetic and pharmacological inhibition of myostatin, and the resultant resistance-trained phenotype, on the prevention and treatment of obesity and type 2 diabetes mellitus." (PMID 23690769, 2013). "Although loss of muscle mass is a clear clinical feature of type 2 diabetes, it is uncertain whether increased circulating myostatin plays a role in the metabolic deterioration of skeletal muscle in individuals with obesity and insulin resistance." (PMID 22615949, 2012). "Future studies should be designed to determine whether inhibition of myostatin signaling can help to reverse established obesity, hepatic steatosis and glucose intolerance." (PMID 21390326, 2011). "This diet-induced obesity is attenuated in mice in which there is marked hypermuscularity caused by constitutive absence of functional myostatin or constitutive expression of a protein that inhibits myostatin activity." (PMID 21390326, 2011). "In obesity, elevated myostatin levels have been reported to be associated with insulin resistance, muscle atrophy, and activation of SMAD2/3 signaling, while experimental and preclinical studies indicate that myostatin inhibition can improve glucose homeostasis and increase lean mass." (PMID 41596614, 2026). "Furthermore, in high-fat diet-induced obesity-susceptible C57BL/6 mice, consumption of high-fat feed led to an increase in MSTN expression, indicating that MSTN may play an essential role in mediating obesity." (PMID 39340593, 2025). "Indeed, MSTN inhibition protects rodents from obesity and insulin resistance." (PMID 40171198, 2025). "Furthermore, the causative factors responsible for the reported upregulation of myostatin with obesity and ageing remain unclear." (PMID 37801203, 2024). "Thus, the underlying factors responsible for the obesity-mediated upregulation of myostatin remain to be elucidated but appear not to be mediated by ageing or insulin resistance per se." (PMID 37801203, 2024). "Our data suggest that higher serum myostatin levels are associated with lower insulin sensitivity in otherwise healthy adults, aged 20–65 years, with overweight/obesity, independent of other risk factors known to be associated with insulin resistance, namely BMI, visceral adiposity, and sex." (PMID 39261976, 2024). "However, no previous studies have examined the association among myostatin, skeletal muscle reduction, and obesity in an apparently healthy population." (PMID 39562792, 2024). "However, myostatin may function as an energy modulator in obesity, as studies have shown that trained obese mice exhibit increased ACTRIIb expression in brown adipose tissue compared to sedentary mice, while no such increase was observed in visceral fat." (PMID 39683624, 2024). "Similar result was also observed that the depletion of MSTN could reduce the age-related adipose tissue mass increase and partially reduce the obesity and diabetic phenotypes in agouti lethal yellow (Ay) and obese (Lepob/ob) mouse models of obesity and diabetes." (PMID 37288303, 2023). "However, there is still disagreement about the role of MSTN in obesity." (PMID 37288303, 2023). "Rb1 may ameliorate obesity in part through the MSTN/FNDC5 signalling pathway." (PMID 35639355, 2022).
Obesity (continued). "Here, we summarize three candidate myokines (IL-6, FNDC5 and MSTN); we speculate that they may exert effects on the recruitment and polarization of macrophages in adipose tissue, thus regulating inflammation states in obesity." (PMID 35273574, 2022). "Interestingly, FMOD gene expression was diminished in aged and HFD mouse muscles and in C2C12 cells cultured in the presence of ceramide or under adipogenic conditions during differentiation, whereas the expressions of genes related to aging, diabetes, and obesity and that of MSTN were all elevated." (PMID 34440852, 2021). "Furthermore, MSTN−/− mice have been reported to have more muscle mass, less fat mass, and more resistance to diet and genetically induced obesity, and a decrease in the role and number of MSCs during aging was reported to result in loss of nuclei in large fibers." (PMID 34440852, 2021). "However, myostatin‐deficient mice also develop insulin resistance via alterations in AMPK activity 148, highlighting the need to determine the exact effects of myostatin signaling, as well as of other myokines correlating with obesity, in whole‐body energy homeostasis." (PMID 31423716, 2019). "Due to the broad impact of MSTN on myogenesis, fat metabolism and glucose metabolism, high levels of myostatin have been shown to lead to muscle wasting that is associated with a variety of diseases, such as cancer, HIV infection, liver disease, obesity, insulin resistance and type II diabetes." (PMID 29541418, 2018). "In addition, the MSTN KO mice also exhibited resistance to diet-induced obesity." (PMID 28344633, 2017). "Thus, it is possible that in obesity a large amount of myostatin could be secreted from adipose as a result of hypercortisolemia." (PMID 24381559, 2013). "We hypothesized that the A55T and K153R polymorphisms in the Myostatin gene may have an association with obesity, abdominal and truncal adiposity and LBM in non-diabetic Asian Indians." (PMID 22916099, 2012). "Mice with obesity-inducing genetic mutations also are leaner when myostatin is absent." (PMID 21390326, 2011). "Furthermore, the expression of Mstn, Fstl3, and Acvr2b is upregulated in adipocytes from obese mice suggesting myostatin signaling may play a role in the response of adipocytes to obesity." (PMID 19295913, 2009). "Additionally, varying the degree of muscle hypertrophy by treatment with different doses of myostatin antagonists will help determine whether there is a threshold level of hypertrophy required for a reduction in obesity." (PMID 19295913, 2009). "Myostatin (GDF-8), frequently elevated in obesity and early T2D, exerts potent anti-anabolic and anti-oxidative effects and signals through the SMAD (mothers against decapentaplegic homolog) family of transcription factors, particularly SMAD2/3." (PMID 41515940, 2025). "Taken together, these data suggested that deletion of FAPs-derived follistatin enhanced MSTN/activin A/p-SMAD2/3 pathway, thereby accelerating skeletal muscle dysfunction in obesity." (PMID 41272451, 2025). "The myokine myostatin (GDF-8) is a potent negative regulator of skeletal muscle growth that is upregulated in humans and animal models of obesity and in T1D patients, and downregulated following regular exercise." (PMID 40429969, 2025). "In contrast, inhibition of myostatin signaling in skeletal muscle leads to increased lean mass, decreased fat mass in mice fed a HFD and resistance to diet‐induced obesity." (PMID 39764565, 2025). "Current evidence exists to support the fact that the inflammatory milieu in obesity, characterized by elevated levels of TNF-α and other adipokines, exacerbates dysregulation of myokines such as myostatin and irisin." (PMID 39683624, 2024). "This study investigated the effects of three different interval resistance training (IRT) protocols and their effects on anthropometric indices, cardiometabolic markers, and levels of decorin, follistatin, myostatin, activin A, TGF-β1 in men with obesity." (PMID 35757424, 2022).
Obesity (continued). "We determined the effects of IRT on the levels of select myokines (decorin, follistatin, myostatin, activin A, TGF-β) and cardiometabolic and anthropometric measures in males with obesity." (PMID 35757424, 2022). "For follistatin and myostatin, differences with the reference values were accentuated in class III obesity, while for irisin the difference was accentuated in class I and II obesity." (PMID 32316563, 2020). "Although, both anabolic and catabolic pathways are well described, i.e., AKT inhibits FoxO and myostatin-SMAD 2/3 inhibits AKT, the exact regulation of protein metabolism during obesity is still incompletely characterized." (PMID 30286093, 2018). "In addition, conditioned medium from myotubes derived from humans with extreme obesity inhibits proliferation of C2C12 myoblasts, an effect that is abolished in the presence of an anti-MSTN antibody." (PMID 40171198, 2025). "Ongoing clinical trials with bimagrumab aim to explore its potential in treating obesity; however, no MSTN inhibitor has received approval for use in metabolic syndromes." (PMID 39340593, 2025). "The mechanism by which myostatin is upregulated in obesity has not yet been fully established; however, canonical myostatin signalling activates SMAD2/3 which represses muscle regulatory factors (MRFs), including MyoD." (PMID 37801203, 2024). "To date, cross-sectional studies in humans have predominantly investigated myostatin expression in middle-aged and aged individuals with and without obesity." (PMID 37801203, 2024). "It is known that GH participates in the close relationship between factors that repress the development and differentiation of muscle fibers, such as myostatin, and that in the MSG-induced obesity model, GH-secreting hypothalamic nuclei are affected, altering GH secretion." (PMID 36902158, 2023). "As a molecule downstream of MSTN, FNDC5 also plays an important role in obesity and diabetes." (PMID 35639355, 2022). "Our data indicate that the remarkable protection from obesity and its sequelae seen in myostatin null mice is not dependent on the activation of beige fat." (PMID 33220490, 2021). "The increased beige fat noted in Mstn-/- mice raises the possibility that this tissue is responsible for the protection from obesity and its complications in the absence of myostatin." (PMID 33220490, 2021). "•Myostatin null mice remain protected from obesity and insulin resistance even in the absence of beige fat." (PMID 33220490, 2021). "Myostatin inhibitors and myostatin deletion in rodents has not only shown to increase muscle mass, but also protect against the negative effects of obesity by preventing insulin resistance and accumulation of body fat, and enhancing fatty acid oxidation." (PMID 33801275, 2021). "Myostatin expression and abundance is reportedly, though not universally, elevated with obesity, advancing age and muscle wasting, and decreased by weight loss." (PMID 33528828, 2021). "Regarding a general approach to a patient’s nutrition status we first applied the BMI to investigate differences in Myostatin concentrations in patients with and without obesity." (PMID 32784522, 2020). "The results indicated that specific inhibition of MSTN in skeletal muscle but not fat tissues can increase resistance to diet-induced obesity." (PMID 28344633, 2017). "Intriguingly, our data comprehensively demonstrates that myostatin deletion is not beneficial against the development of obesity and fat tissue accumulation." (PMID 26644908, 2015). "To date, no work has been conducted to characterize the expression myostatin and its receptor against the setting of obesity in the horse or pony." (PMID 25390640, 2014). "Thus, 16 weeks of n-3 supplementation and of RT alone, but not in combination, decreased myostatin circulating levels in postmenopausal women with overweight/obesity in the absence of changes in skeletal muscle mass." (PMID 40806137, 2025).
Obesity (continued). "We addressed these limitations by studying a group of otherwise healthy adults with overweight/obesity and without type 2 diabetes or other end‐organ dysfunction, and by measuring fasting serum myostatin levels using a validated LC–MS/MS assay with excellent sensitivity and specificity." (PMID 39261976, 2024). "Thus, neither the induction of insulin resistance nor cross-talk with SAT is able to explain the obesity-mediated upregulation of myostatin in ageing." (PMID 37801203, 2024). "Increased mRNA myostatin and ActRIIb could be retrieved in visceral and subcutaneous fat of mice models of obesity as well as in non-diabetic obese patients." (PMID 39683624, 2024). "Additionally, myostatin increases with obesity and with a lack of exercise, which is involved in the acquisition of insulin resistance." (PMID 36981616, 2023). "Studies have explored the impact of MSTN on insulin resistance, and several studies conducted using mouse models have provided evidence that the absence of MSTN has significant effects on metabolism, that is, it improves insulin sensitivity and reduces obesity." (PMID 35812316, 2022). "In this prospective study, we show that myostatin levels start to rise during adolescence in males with severe obesity, which could potentially have negative health consequences, as previously reported for elevated myostatin levels." (PMID 35631274, 2022). "Although many emerging pharmacological interventions have been studied, such as testosterone supplementation, selective androgen receptor modulators, myostatin inhibitors, and anti-obesity drugs, there are no approved drugs for the treatment of SO in the elderly." (PMID 35371597, 2022). "Overall, our findings of increased transcriptional activation of genes involved in ubiquitination and proteasomal degradation and myostatin signalling in muscle of patients with T2D compared with obesity alone were not supported by the abundance of proteins in the ubiquitin-proteasomal system." (PMID 35805088, 2022). "In addition, serum myostatin levels were elevated along with an increase in the insulin level, independent of skeletal muscle mass, in patients with obesity." (PMID 33465151, 2021). "A recent review has identified that myostatin may play an important role in contributing to the negative cycle of obesity by not only adversely regulating muscle mass but also reducing lipid oxidation and insulin sensitivity." (PMID 33801275, 2021). "Protection from obesity by increasing muscle mass is not unique to the myostatin pathway." (PMID 33220490, 2021). "Moreover, myostatin knockout mice have significantly improved insulin sensitivity and glucose uptake, have increased peripheral tissue FAO, and are protected from diet-induced obesity." (PMID 29697773, 2018). "Importantly, this increased loss of muscle with the high-fat diet does not appear to be related to circulating glucose or elevated myostatin levels, both known complications of prolonged obesity." (PMID 26539241, 2015). "All research in this area, including the present study, has examined whether lack of myostatin activity attenuates the development of obesity or hyperglycemia when myostatin activity was knocked out or inhibited before the mice became obese." (PMID 21390326, 2011). "Interestingly, adults with polymorphisims in the Myostatin (MSTN) gene display higher waist circumference and total fat mass, implying that variations in the MSTN gene may be an influential factor related to abdominal adiposity and obesity." (PMID 35287731, 2022). "However, in our HFD-fed mice myostatin expression in muscle was not higher and therefore, the effects of neither the anti-myostatin PMO, nor the myostatin propeptide, can be ascribed to the counteraction of an obesity-associated increase in myostatin expression." (PMID 33452345, 2021).